CXCR3 (C-X-C motif chemokine receptor 3)
Diseases named in the same sentence as CXCR3 in open-access papers (continued):
Sharing a sentence is not in itself a finding about the gene and the disease.
tumor (continued). "IFN-γ enhances antigen presentation by dendritic cells and stimulates production of the CXC chemokines MIG (CXCL9) and IP-10 (CXCL-10), which inhibit tumor angiogenesis and recruit CXCR3-bearing effector cells to tumor sites." (PMID 26458364, 2015). "Given the upregulation of IL-8 expression in BOWES CXCR3 cells in vitro, we examined expression of IL-8 mRNA in tumor tissue." (PMID 25798946, 2015). "Using immunofluorescence staining of the tumor tissues, we initially observed a higher level of CXCR3 at the invading edge of the tumors." (PMID 26485767, 2015). "Our findings demonstrate that targeting CXCR3 is effective in both tumor and host compartments, and suggest that CXCR3 inhibition is likely to avoid adverse effects on host cells." (PMID 26485767, 2015). "There was also a further highly significant enrichment of CXCR3+ T cells in the tumour compared with NDLN and TDLN." (PMID 25495686, 2015). "Deletion of CXCR3 in host cells using CXCR3 KO mice showed a decreased metastasis and improved host anti-tumor immunity." (PMID 26485767, 2015). "When we analysed tumor-infiltrating T cells for CXCR3 expression, a high proportion (approximately 60%) of tumor-infiltrating Tregs were CXCR3+." (PMID 26433463, 2015). "Here we report that targeting CXCR3 decreased tumor cell migration and at the same time improved host anti-tumor immunity." (PMID 26485767, 2015). "When the frequencies of CD4+ CXCR3+ T cells were compared among the input and migrated fractions recovered from the tumour, a significant enrichment of CXCR3+ CD4+ T cells was found P = 0·009." (PMID 25495686, 2015). "Based on the observation that CXCR3+ T cells are significantly enriched in MCA-induced tumours, we postulated that the CXCR3-binding chemokines (such as CXCL10) were likely candidates for recruitment of T cells to the fibrosarcomas." (PMID 25495686, 2015). "In the case of CXCR3, although we found that a greater proportion of Foxp3+ T cells, compared with Foxp3– T cells, expressed CXCR3 in tumours, CXCR3 was more prevalent on both cell types when comparing tumours to lymph nodes." (PMID 25495686, 2015). "Mouse (host) microarray analysis showed a significant increase in the NK cell damage response receptor CXCR3, which binds tumor-cell specific membrane-bound activation ligands CXCL9, CXCL10, and CXCL11, all of which were also increased on the human array." (PMID 25952672, 2015). "In our study, using genetic approaches of RNA interference and KO mice, as well as a small molecular inhibitor, we found that targeting CXCR3 not only directly inhibited tumor cell migration and mobility, but also improved host immune responses." (PMID 26485767, 2015). "Correspondingly, CD8+ T lymphocytes were more frequently CCR5- and CXCR3-positive in tumor than in peripheral blood." (PMID 26317795, 2015). "Mice bearing 4T1 CXCR3 KD cells had significantly reduced lung metastasis compared to the controls, suggesting CXCR3 plays a critical role in promoting tumor metastasis." (PMID 26485767, 2015). "Instead, CXCR3 marks a population of activated Foxp3− and Foxp3+ T cells, which use multiple and overlapping ligand receptor pairs to guide their migration to tumours." (PMID 25495686, 2015). "Together these data suggest that CXCR3 is likely important in tumor metastasis and its expression is likely up-regulated by the tumor microenvironment." (PMID 26485767, 2015). "Taken together, these data show that, compared to mice injected with BOWES PCMV6 cells, mice injected with BOWES CXCR3 cells had decreased tumor latency and increased tumor growth rate." (PMID 25798946, 2015). "First and most importantly, the promiscuity of CXCR7 ligands and the widespread expression of CXCR4 and CXCR3 in tumor tissues makes the dissection of CXCR7-specific signaling particularly challenging." (PMID 23894550, 2013).
tumor (continued). "Once anchored into the cell membranes of endothelial cells, the mucin domain together with the chemokine head should concertedly induce rolling and tight adhesion of CXCR3+ leukocytes, followed by diapedesis into the tumor tissue." (PMID 24023642, 2013). "Conversely, in ovarian cancer, tumor-infiltrating Treg were enriched in CXCR3+ cells, highly expressing T-bet but poorly producing IFN-γ, and strongly suppressing Th1 response ex vivo." (PMID 23986759, 2013). "In our study, preferential homing of Th1 CD4 T cells to intracranially implanted tumours correlated with high expression of CXCR3, which is a receptor for IFN-γ-inducible protein (IP)-10/CXCL10." (PMID 23717511, 2013). "Such recruitment to tumor sites occurs via CXCR3 mediated chemotaxis in response to the CXCL9-11 chemokines, produced within the TME." (PMID 23326300, 2013). "For T cell migration to brain tumours, very-late antigen (VLA)-4 (α4β1 integrin) and CXCR3 are particularly well defined as playing key roles for tumour-reactive CD8 T cells." (PMID 23717511, 2013). "Th1 cells expressed high levels of α4 integrin and CXCR3 and homed more efficiently to the brain of tumour bearing mice than Th2 cells." (PMID 23717511, 2013). "CD4+ Th1 lymphocytes expressing CXCR3 have been shown to be important for anti-tumor responses, and the reduction in CXCR3+ cells probably mirrors a reduction of Th1 cells and CD8+ CTL in the tumor area." (PMID 22319577, 2012). "Although CXCR3 is expressed in cytotoxic T cells, several studies demonstrated that CXCL9 and CXCL10 induced migration of CXCR3+ tumor cells, suggesting that CXCR3+ tumor cells preferentially metastasize to lymph nodes expressing these ligands." (PMID 24213462, 2012). "We show here that the frequencies of CXCR3+ conventional T cells are significantly reduced in tumor compared to unaffected mucosa from the same patient." (PMID 22319577, 2012). "Accompanying this profile was a reduction in the endothelial markers MECA 32 in the tumor but an increase in CXCR3 expression." (PMID 22815789, 2012). "To further evaluate differences between high and low avidity T cell function in tolerized mice, we analyzed CXCR3 expression on both high avidity and low avidity T cells on days 3 and 5 after adoptive transfer into tumor-bearing neu-N mice." (PMID 22359647, 2012). "CXCL9 is produced in the tumor-microenvironment in response to IFNγ production, and can attract CXCR3+ T cells into the tumor." (PMID 22359647, 2012). "High β1 integrin, LFA-1, and CXCR3 expression on CD25low Tregs allow for increased blood vessel extravasation and migration into the tumor, while the low levels of CD62L indicate a migratory phenotype." (PMID 22359647, 2012). "The reduction in CXCR3+ cells in the tumor stand out in comparison with expression of many other chemokine receptors, which were similar in the tumor and unaffected mucosa." (PMID 22319577, 2012). "Recent study has demonstrated that CXCR3 inhibitor decreased the proliferation, survival and invasion of the tumor cells in an animal model of OS lung metastasis." (PMID 22448123, 2012). "In other words, the interaction between CXCR3 and its ligands can directly enhance the invasion, survival, and proliferation of tumor cells in the metastatic organ." (PMID 22448123, 2012). "There was a positive correlation between macrophage density and CXCR3 expression (rs = 0.520, p = 0.02) and between mast cell density and CXCR3 expression (rs = 0.499, p = 0.03) in the tumour islets." (PMID 20429924, 2010). "There was an association between 5 year survival and tumour islet CXCR2, CXCR3 and CCR1 density (p = 0.02, 0.003 and <0.001, respectively) as well as stromal CXCR3 density (p = 0.003)." (PMID 20429924, 2010). "It is thus conceivable that CXCR3 blockade through systemic antagonism in the environment of lung metastases contributed to interfere with tumour development." (PMID 19436305, 2009).
tumor (continued). "Here, we show that activation of CXCR3 by its ligands results in both human and mouse tumour cell proliferation, survival and chemotaxis." (PMID 19436305, 2009). "Finally, dual inhibition of FGFR4 and CXCR3 suppressed tumor growth, accompanied by CAF downregulation." (PMID 40447617, 2025). "Indeed, we observed that the preferential expression of CD49a and CD69 correlated with the ability of NK cells to infiltrate the tumor via CXCR3." (PMID 40168086, 2025). "However, recent studies revealed that the autocrine CXCL9, −10, −11/CXCR3 axis in tumor cells facilitates proliferation, angiogenesis, and metastasis as well as reduced CXCR3 expression on CD8+ T cells." (PMID 40447617, 2025). "Moreover, the expression of CXCR3 and its ligands correlates with the presence of effector T cells in tumor tissues and with patients’ disease-free survival." (PMID 40786052, 2025). "On the other hand, some studies suggest that CXCL9/CXCR3 may contribute to tumor progression and metastasis." (PMID 40145607, 2025). "External PDAC datasets supported these findings, i.e., single-cell RNA-seq showed that CXCR3 is mainly expressed by tumor-infiltrating CD8+-T-cells, and TCGA data analysis found that CXCR3 expression correlated strongly with activated/effector memory CD8+-T-cells." (PMID 40696453, 2025). "Therefore, we chose to inhibit the CXCL9 pathway via its receptor CXCR3, as this cytokine has been described as influencing tumor cell growth." (PMID 40362215, 2025). "Moreover, Cxcr3-expressing Th1-like CD4+ T cells have been shown to be induced as nanoparticles that target tumor-draining lymph nodes, which is consistent with our nanomedicine that targets the tumor niche." (PMID 40530387, 2025). "For example, CXCL9/CXCR3, which is known to recruit cytotoxic T cells, may counteract the tumor‐promoting effects of CXCL12/CXCR4 by enhancing anti‐tumor immunity." (PMID 40145607, 2025). "Furthermore, TILs inherently express chemokine receptors (e.g., CCR5, CXCR3), facilitating homing to tumor sites and enhanced infiltration into the tumor microenvironment (TME) post-reinfusion, which amplifies their localized cytotoxic efficacy." (PMID 40458394, 2025). "In summary, these results suggest that the miR-762/CXCR3 axis may regulate T-cell activation, polarization, proliferation, and IL-12 secretion in the tumor microenvironment." (PMID 39940842, 2025). "Notably, TGF-β contributes to immunosuppression through the downregulation of CD8+ T-cell expression of CXCR3, limiting trafficking to the tumour site." (PMID 40361472, 2025). "Also, CXCR3 plays a crucial role in stabilizing intravascular adhesion of T cells, facilitating their extravasation into the tumor tissue." (PMID 41041322, 2025). "Another topic discussed in this review is the role of the CXCR3 axis in MM tumor processes." (PMID 40940985, 2025). "Interestingly, Ncr1ΔCxcr3 mice displayed increased metastasis incidence at 15 days and increased tumor burden at 20 days postinjection, indicating a role for CXCR3+NKp46+ cells in protection from metastasis." (PMID 40168086, 2025). "Inhibition of CXCR3 on T-bet+ hTregs could hinder their migration to tumor sites, potentially reducing their ability to suppress local immune responses." (PMID 41041322, 2025). "CXCL10 binds to its receptor CXCR3, thereby recruiting T cells to the tumor." (PMID 41463372, 2025). "In addition, A. muciniphila promotes the infiltration of CD4+ CCR9+ CXCR3+ T cells into the tumor site, thereby supporting a strong Th1-skewed immune response—an essential component for effective tumor control." (PMID 41030253, 2025). "Thus, L-TTF2 tumors are infiltrated by more cytotoxic CXCR3+-T-cells that can engage with tumor cells and likely increase tumor cell apoptosis." (PMID 40696453, 2025). "CXCL10, through its receptor CXCR3, plays a dual role in tumor immune escape." (PMID 41376630, 2025).
tumor (continued). "The increased CXCR3 signaling may lead to the suppression of NK cell function, thereby promoting a “nurturing” phenotype that supports tumor growth and immune evasion." (PMID 40786052, 2025). "The intratumoral injection of STING agonists has shown great promise in preclinical cancer models and leads to an enhanced content of the tumor-intrinsic type I IFNs, increased C-X-C motif chemokine receptor 3–dependent (CXCR3-dependent) antitumor immunity, and increased survival." (PMID 41129257, 2025). "Moreover, CXCL10/CXCR3 decreased tumor angiogenesis and increased cell apoptosis in vivo and in vitro." (PMID 40781073, 2025). "While this could reflect a distinct role for CXCR3 during early tumor development, our data point towards a more fundamental mechanistic difference between the two inhibitory approaches." (PMID 41516196, 2025). "We could also support the finding that the CXCR3 axis has an inhibitory effect on tumor cell growth." (PMID 40362215, 2025). "Furthermore, treatment with the selective CXCR3 antagonist AMG487 reduced tumor growth and disrupted mitochondrial function in vitro, in vivo, and in patient-derived GBM stem cells." (PMID 40185710, 2025). "Similarly, in LGG, we found that a low WWOX/HIF1A ratio fosters invasive phenotypes through HIF-1α-induced VEGF signalling and overexpression of CXCR chemokine receptors (CXCR3/4/5/6), which collectively drive angiogenesis and tumour dissemination." (PMID 41007296, 2025). "The chemokine receptor CXCR3 plays a critical role in tumor angiogenesis and cell migration." (PMID 40786052, 2025). "It remains unclear whether the IFN-γ/STAT1 signaling regulates the immune escape for tumor progression demonstrated here by CXCL10/CXCR3." (PMID 40909948, 2025). "Targeting CXCR3 could enhance anti-tumor immune responses, offering a new strategy for cancer treatment." (PMID 40786052, 2025). "Notably, in the context of squamous cell carcinoma of the tongue, CXCL9 has been demonstrated to interact directly with tumor cells via its receptor CXCR3, thereby promoting tumor invasion and metastasis." (PMID 40909948, 2025). "We investigated whether treatment with FGFR4 and CXCR3 inhibitors can suppress tumor growth and CAF differentiation." (PMID 40447617, 2025). "Notably, however, our data also illustrates a strong induction of TH1‐type chemokines CXCL9, CXCL10 and CXCL11, which are ligands for CXCR3 and critical to drive T‐cell recruitment to the tumour sites." (PMID 39743376, 2025). "Furthermore, CXCL9/10-expressing cDC1 and IFN-γ-stimulated tumor cells can also recruit CXCR3+ TRM or TE cells into tumors through T cell tumor infiltration." (PMID 41194931, 2025). "Mechanistically, our data reveal that COUP-TFII-induced reversal of tumor immune evasion relies on T cells, correlates with increased effector T cell recruitment, and depends on vascular selectins and T cell CXCR3 to facilitate effector T cell homing to the tumor." (PMID 40796746, 2025). "Additionally, cytotoxic CXCR3+CD8+-T-cells were found more frequently in PanCK+ tumor areas from L-TTF2 than S-TTF2 patients (42.5% vs. 16.6% of these T-cells localized to tumor cells, P = 0.0042)." (PMID 40696453, 2025). "However, CXCR3 also recruits regulatory T cells (Treg) to the tumor microenvironment, inhibiting the immune system’s anti-tumor response." (PMID 40940985, 2025). "Notably, CXCL9, CXCL10, and CXCL11 utilize the shared receptor CXCR3 and engage in similar mechanisms that facilitate the recruitment of T cells and other immune cells to the tumor microenvironment, contributing to antitumor responsiveness." (PMID 40909948, 2025). "Despite this, reactive T cells continue to express CXCR3 even in tumor-stage MF." (PMID 40861461, 2025). "To clarify whether PRMT5 directly regulates the CXCL10/CXCR3 signaling pathway, we established tumor models in CXCR3 KO mice with control cells and PRMT5 knockdown U14 cells." (PMID 41463372, 2025).
tumor (continued). "However, it should be noted that the correlations between CD16, CD25, or CXCR3 expression and anti-tumor function were observed by investigating γδ T cells’ activity against the Daudi cell line." (PMID 41369406, 2025). "Interestingly, in the NKim subset, expression of IL15 and inhibitory receptor KLRG1 increased significantly with tumor progression; chemokine receptor CXCR3 expression increased with tumor grade in both NKctx and NKim cells." (PMID 40821787, 2025). "Given the increase in Cxcl9/10 mediated signals from mdTAMs following anti-PD-L1 treatment, we hypothesised that Cxcr3-expressing T cells would localise to the tumour core, where mdTAMs were enriched." (PMID 40523200, 2025). "However, we observed that CXCR3i damages the antitumor effects of oHSV therapy and inhibits CXCR3 expression in CD8+ T cells of tumours." (PMID 39219056, 2025). "The receptor CXCR3 is widely expressed on activated T cells, natural killer (NK) cells, and other immune subsets, facilitating the chemotaxis of these effector cells into the tumor microenvironment (TME)." (PMID 40557143, 2025). "Dual inhibition of FGFR4 and CXCR3 suppresses tumor growth through CAF downregulation." (PMID 40447617, 2025). "Importantly, upon CXCR3 blockade, iCoup-mediated tumor inhibition was abolished, phenocopying the effect of T cell depletion." (PMID 40796746, 2025). "In an orthotopic pancreatic tumor model, targeting tumor-initiating cells (TICs) with MSC membrane-derived nanovesicles, known as “nano-ghosts,” loaded with a CXCR3 antagonist improved treatment efficacy and delayed tumor recurrence when combined with gemcitabine." (PMID 40078996, 2025). "Given CXCL10’s canonical role as a chemoattractant, local elevation of CXCL10 within OS lesions may also facilitate recruitment of CXCR3+ circulating monocytes and macrophages, amplifying the immunosuppressive and tumor-promoting microenvironment." (PMID 41516196, 2025). "This suggests that miR-762 may influence the alternative splicing or transcriptional regulation of CXCR3 isoforms, thereby shaping their distinct roles in tumor progression and immune modulation." (PMID 39940842, 2025). "In these cases, CXCR3 antagonists ‎could be ‎used to block the tumor’s ability to use CXCL10 for immunosuppression, while in other ‎‎cases care must be taken to preserve the positive immune-activating effects of CXCL10." (PMID 40760734, 2025). "Effector cells like CD8+ T-cells and NK cells rely on CXCR3 to infiltrate tumours." (PMID 40361472, 2025). "The chemokine and receptor profiles of tumor-infiltrating NK1 and NK5 showed increased expression of CCL5, CCL4, XCL1, XCL2, and CXCR3, suggesting that they may be involved in NK tumor homing and activation." (PMID 40315330, 2025). "However, the TME of IL-1α KO tumors showed higher expression of CXCR3 ligands, such as CXCL9/10, which can attract anti-tumor CXCR3+ CTL, and Th1 lymphocytes, and NK cells." (PMID 38612760, 2024). "This may provide a gradient sufficient for tumour-specific CXCR3+ CD8+ T cells to migrate into the respiratory tract." (PMID 38271469, 2024). "In malignancies, CXCR3 affects tumor progression by recruiting effector T cells." (PMID 38213736, 2024). "As a result, targeting CXCR3 signaling pathways by CXCL9/10 could be a promising anti-tumor strategy." (PMID 38953994, 2024). "We report that in addition to attracting CXCR3+ T cells to tumor sites a key role of CXCL9 and CXCL10 is in inducing a self-feeding feedback loop that accelerates effector/cytotoxic activities of both CD4+ and CD8+ T cells while downregulating immunoregulatory protein TIM3." (PMID 39474427, 2024). "CXCR3 might contribute to recruiting cytotoxic T cells and natural killer cells to the tumor microenvironment, thus enhancing the immune response against NBL cells and affecting tumor growth and metastasis." (PMID 39559348, 2024).